HIF1A (hypoxia inducible factor 1 subunit alpha)
Diseases named in the same sentence as HIF1A in open-access papers (continued):
Sharing a sentence is not in itself a finding about the gene and the disease.
cancer (continued). "However, HIF-1α target genes are also involved in other critical aspects of cancer biology, including cell survival, chemotherapy and radiation resistance, immortalization, immune evasion, metastasis, and metabolism." (PMID 36745547, 2023). "A previous study showed that simultaneous blockade of PD-L1 and inhibition of HIF-1α may represent a novel approach for cancer immunotherapy." (PMID 37906252, 2023). "HIF-1α is a transcription factor essential for cancer cell survival." (PMID 36766828, 2023). "HIF-1α also alters glucose, fatty acid, and amino acid metabolism to support cancer cell survival." (PMID 36761981, 2023). "It promotes cancer cell metastasis by upregulating HIF1α expression." (PMID 37583933, 2023). "Interestingly, XBP1 interacts with HIF1α and assembles a transcriptional complex to regulate a set of genes, which promote cancer progression in TNBC." (PMID 37583933, 2023). "The HIF-1α pathway plays an indispensable role in glucose metabolism in cancer cells." (PMID 37204526, 2023). "Activation of HIF-1A is one of the most common features in human cancers." (PMID 36978001, 2023). "Several miRNAs inhibit apoptosis in cancer cells with the involvement of HIF1A." (PMID 36835100, 2023). "Our findings indicate that such selectivity in HIF-1α expression within chronic hypoxia might contribute to distinctive cancer traits." (PMID 37777750, 2023). "SIRT3 could reprogram cancer cell metabolism through HIF1α destabilization or suppress HIF‐1α by reducing mitochondrial ROS." (PMID 36383055, 2023). "HIF-1α is known to be overexpressed in a number of cancer types." (PMID 36766555, 2023). "In addition, PX-12 downregulates the expression of vascular endothelial growth factor (VEGF) by decreasing HIF-1α, thereby inhibiting cancer metastatic cells." (PMID 37749603, 2023). "Mainly, hypoxia induces activation of hypoxia inducible factor 1-alpha (HIF-1α) and its downstream genes related to cell metabolism, survival, movement, basal membrane integrity, angiogenesis, and hematopoiesis, which promotes cancer cell proliferation, invasion and metastasis." (PMID 36945005, 2023). "Several miRNAs modulate necroptosis is cancer cells with the involvement of mTOR and HIF1A." (PMID 36835100, 2023). "LncRNA, Metallothionein 1 J, pseudogene (MT1JP), may suppress cancer cell proliferation and migration by transcriptionally activating miR-138, which directly targets HIF1α mRNA transcripts." (PMID 37583933, 2023). "Moreover, HIF-1α is activated by various stimuli, even under normoxic conditions, and plays an important role in the metabolic reprogramming of cancer cells." (PMID 38052785, 2023). "Accordingly, SREBP1, 4EBP1, and HIF1A regulate the miRNA-mediated migration of cancer cells." (PMID 36835100, 2023). "For example, H2O2 could oxidize prolyl hydroxylase domain protein 2 (PHD2) and lead to the stabilization of hypoxia-inducible factor 1α (HIF-1α), a protein that is essential for angiogenesis and cancer metastasis." (PMID 37528424, 2023). "In addition, some mitochondrial DNA mutations increase ROS levels, resulting in increased Akt (also known as protein kinase B, PKB), MAPK (mitogen-activated protein kinase), and HIF-1α-dependent signaling pathways, thereby promoting cancer progression." (PMID 37760037, 2023). "The HIF-1α/VEGF signaling pathway has been recognized to play a crucial role in cancer metastasis." (PMID 37718440, 2023). "However, baicalein was more effective in inhibiting cancer cell proliferation and HIF-1α, c-Myc, NF-κB and VEGF expression." (PMID 37446743, 2023). "In a word, the HIF1α pathway plays an important role in the treatment of cancer." (PMID 37790761, 2023). "Thus, targeting HIF-1α is considered a promising strategy for inhibiting cancer cell proliferation and overcoming chemoresistance." (PMID 37175841, 2023). "In addition, RT–qPCR was performed to compare Hif1a expression between the sorted cancer cells (GFP + /CD45-) from the IP + LC and LC models." (PMID 38012636, 2023).
cancer (continued). "Some studies showed that curcumin could inhibit the proliferation and progression of several cancers by decreasing the expression of HIF-1α, STAT3, or VEGF signaling molecules, as well as inducing cell apoptosis." (PMID 37333486, 2023). "Furthermore, studies have found that YAP interacted with HIF-1α to directly activates the transcription of glucose metabolism genes and accelerate glycolysis in cancer cells 19-20." (PMID 36594102, 2023). "Herein, we designed a hypoxia-sensitive CRISPR–Cas9/dCas9 system by conjugating the oxygen-sensitive domain of HIF-1α to the effector Cas9/dCas9 protein and analyzed the functional activity of this conjugate system and its potential application in cancer therapy." (PMID 37798384, 2023). "Hypoxia-inducible factor-1α (HIF-1α) is a potential therapeutic target for many types of cancer." (PMID 37558230, 2023). "In addition, volatile anesthetics can upregulate the hypoxia-inducible factor 1α (HIF1α), which confers protective effects on cancer cells, and the vascular endothelial growth factor, which can stimulate the growth of cancer cells and neovascularization." (PMID 37114153, 2023). "Some of the drug groups mentioned as senolytics, like HDAC inhibitors, which also have anti-HIF-1α action may be promising to overcome therapy resistance in cancer." (PMID 36846589, 2023). "This could help in OSCC patient stratification and personalize cancer treatment because the HIF-1α pathway is a potentially treatable and‘druggable’ target." (PMID 36766555, 2023). "The STAT3/HIF-1α signaling pathway exerts a promoting function in various cancers." (PMID 37628777, 2023). "As HIF-1α plays an important role in hypoxia and glucose metabolism, cancer treatment strategies that may help inhibit HIF-1α activity will have broad application prospects." (PMID 37008055, 2023). "Therefore, HIF-1α contributes to cancer cell proliferation, migration, and survival and other processes that include GLUT 1 and cyclin D." (PMID 37176098, 2023). "The overexpression of both Akt2 and HIF-1α is related to cancer progression, besides metabolism." (PMID 38139010, 2023). "Notably, higher levels of HIF-1α were observed in EVs from COPD subjects who subsequently developed cancer compared to those who remained cancer-free." (PMID 37838700, 2023). "Notably, HIF-1α has also been described to regulate self-renewal of CICs, supporting their maintenance and cancer progression and also directly regulates CXCR4 expression." (PMID 37838700, 2023). "In fact, HIF-silenced cells showed a reduction of the PD-L1 expression, which may suggest that constitutively expressed levels of HIF1α in cancer cells drive PD-L1 expression that can be suppressed by HIF-blockage." (PMID 37067635, 2023). "In cancer, the cycle initiated by CD133 and hypoxia causes an increase in HIF-1α formation." (PMID 37841777, 2023). "Several miRNAs modulate ferroptosis in cancer cells with the involvement of mTOR, 4EBP1, and HIF1A." (PMID 36835100, 2023). "PX-478 suppresses HIF-1α in cancer cells in preclinical rodent models and in vitro." (PMID 36831579, 2023). "The expression or increased activity of HIF-1α is closely related to various human cancers." (PMID 38140111, 2023). "This investigation provided evidence that glycine back supplementation canrestore normal HIF1α expression in hypoxic environments, thus revealing a previously unknown role for glycine in cancer biology." (PMID 37108312, 2023). "The KDM4C gene is a HIF-1 target gene; therefore the interaction of JMJD2C with HIF-1α may provide a positive feedback mechanism in cancer cells by amplifying HIF-1–mediated transactivation." (PMID 36899934, 2023). "HIF-1α, which is induced under hypoxic conditions, is an important transcriptional regulator of a number of signaling pathways that mediate the development and progression to cancer." (PMID 37828903, 2023).
cancer (continued). "In addition, attenuation of the agigogenic and invasion activities of cancer cells that are strengthened under acute hypoxic conditions occurs along with degradation of HIF-1α during chronic hypoxia." (PMID 37777750, 2023). "Likewise, HIF-1α also modulated epithelial-to-mesenchymal transition (EMT) through the VEGFA/NRP1 axis in low Gleason grade cancers." (PMID 36376373, 2023). "Interestingly, MUC1 is itself a target of HIF-1α, suggesting the operation of a positive feedback loop in cancer cells under hypoxia." (PMID 36899934, 2023). "In other cancers, hypoxia activates the Hh pathway via HIF-1α." (PMID 36901857, 2023). "Because, most solid tumor cells undergo hypoxia and a number of cancer cell pathways are directed by hypoxia factor, HIF-1a targeted therapy may be a comprehensive approach against solid tumor cancers, in particular CRC." (PMID 37749603, 2023). "Amino acid transporters, including LAT1, can activate mTOR signals and various cancer-related molecules (HIF1A, growth factors, and kinases) through regulation of amino acid metabolism and protein synthesis, leading to cancer stemness and metastatic invasiveness, as well as therapeutic resistance." (PMID 36768934, 2023). "HIF-1α was a critical transcription factor in cancer progression." (PMID 37215053, 2023). "USP33 could also serve as the deubiquitinating enzyme of HIF-1A protein and promote the stability of HIF-1A protein to control the HIF-1A signaling pathway in cancers." (PMID 37322017, 2023). "Increased expression of HIF-1α is predictive of cancer metastasis." (PMID 36984785, 2023). "It was reported that TIMP-2 interacted with pro-cancer factors, like HIF1α and VEGF-A." (PMID 35953652, 2023). "Hypoxia induced abnormal activation of hypoxia-inducible factor-1α (HIF-1α) in the immune microenvironment, and also upregulated LDHA and GLUT1 to cause glycolysis, which promoted the progression of HCC and led to enhanced drug resistance of cancer cells." (PMID 37663261, 2023). "However recent work evaluated the expression levels of HIF-3α in various types of cancer, and interestingly found that in contrast to HIF-1α and HIF-2α, an increase in expression levels of HIF-3α correlated with better survival." (PMID 37886168, 2023). "In order to understand the connections between BIRC5, HIF1A, and FLT4 expression and specific immune cells, we conducted a correlation analysis between these oncogenes and markers of cancer-associated fibroblasts (CAFs), considering the influence of sample purity." (PMID 37509650, 2023). "Finally, it should be mentioned that CDK2 can promote the activity of HIF1A activity in certain cancer cells." (PMID 38276269, 2023). "Among their subunits, HIF-1α has been well studied and is known to activate several downstream genes transcriptionally related to angiogenesis, anaerobic metabolism, and resistance to radiation in cancer tissues." (PMID 35743281, 2022). "It is established that metabolic reprogramming in cancer cells may lead to HIF-1α activation, which reduces E-cadherin expression and promotes the epithelial-mesenchymal transition and cancer cell invasion." (PMID 35008409, 2022). "Given the profound effect of PD-L1 on immune function, it was of interest to test whether HIF-1α inhibition results in an immunotherapeutic effect on cancer." (PMID 35239514, 2022). "The development of drugs targeting HIF1α is critical for the treatment of cancer patients." (PMID 35860430, 2022). "LDHA is almost universally upregulated in cancer cells by c-Myc and HIF-1α." (PMID 36531060, 2022). "With continued exploration of natural endogenous ERRα ligands and understanding of the regulation of HIF-1α, the key goal in the future is to develop drugs that regulate the transcriptional activity of HIF-1α/ERRα to prevent and treat metabolism-related malignant tumors and other diseases." (PMID 35800058, 2022).
cancer (continued). "Alternatively, some approved drugs known to indirectly alter the HIF-1α pathway could also act as adjuvant therapy for existing cancer treatments." (PMID 35499071, 2022). "It has been demonstrated that HIF‐1α regulation glycolysis occurs in cancer cells." (PMID 35615976, 2022). "Enriched pathways for upregulated miRNAs included: “Chemical carcinogenesis–receptor activation” (p-value = 0.018) associated with ESR1, FGF18, JAG1, KPNA6, PPARA genes; the pathway “Proteoglycans in cancer” (p-value = 0.089) associated with genes ESR1, FRS2, HIF1A, PDCD4." (PMID 36359024, 2022). "This section denoted and discussed the mechanisms by which functional mitochondria can support HIF-1α stability and function to improve the cancer cells’ capacity to run glycolysis, responding to their high energy demands, proliferation, and surviving in the hypoxic TME." (PMID 36292613, 2022). "Therefore, simultaneous blockade of PD-L1 and inhibition of HIF1A is a promising approach for cancer immunotherapy and should be thoroughly explored in the near future." (PMID 35659268, 2022). "It is well established that HIF-1α stimulates and protects cancer cells against apoptosis." (PMID 35205167, 2022). "Therefore, the close interaction between HIF-1α and ERRα influences the metabolic and functional changes in cancer cells." (PMID 35800058, 2022). "Hypoxia, and in particular hypoxia-inducible factor 1 alpha (HIF-1α) is a common feature of solid tumors and is involved in metabolic reprogramming of tumors, stem cell characteristics, angiogenesis, extracellular matrix organization and metastasis of cancers." (PMID 35574385, 2022). "We therefore hypothesize that the inhibition of HIF-1α is the principal regulator of melatonin’s pro-oxidant activity in cancer cells." (PMID 36009340, 2022). "Given that HIF1α has oncogenic roles in multiple cancer types, we wondered whether HIF1α might be modulated by SIRT3 in DLBCLs as well." (PMID 35019856, 2022). "They found that HIF1A is a promising molecular marker for the assessment of the sensitivity of cancer cells to platinum compounds, as well as silencing its expression is a factor sensitizing cells to an anti-cancer drug." (PMID 35625926, 2022). "Therefore, the use of hypoxia modulators—especially those interfering with the transcription activity of HIF-1α—holds much promise for improving the therapeutic benefit of cancer immunotherapies." (PMID 35795658, 2022). "Thus, we decided to study the expression of these two nuclear transcription factors involved in metabolic reprogramming of cancer cells and our data showed that resistant cells are characterized by higher levels of HIF-1α and lower levels of c-MYC." (PMID 35459212, 2022). "PMC treatment suppresses the NF-kB pathway, HIF-1α production and cancer cell proliferation." (PMID 35918337, 2022). "The HIF1α pathway and glycolysis were also among the enriched pathways, but with much less significance in comparison to the predominant glycolytic profile described in most hypoxic cancer types." (PMID 35740651, 2022). "Additionally, enhanced production of PA contributes to the activation of hypoxia-inducible factor 1-alpha (HIF1A) transcription that stimulates angiogenesis and cancer cell proliferation." (PMID 36557318, 2022). "Our approach was to characterize the response of different cancer cell lines using different chemotherapeutic agents and then evaluate the impact of combined chemoradiotherapy on the levels of HIF-1α on the same cells under hypoxia taking the normoxic conditions as reference." (PMID 35396948, 2022). "Currently, wogonin has been regarded as a promising reversal agent for multi-drug resistance and may reverse cancer therapy resistance by inhibiting the PI3K/AKT pathway to downregulate HIF-1α expression and glycolytic flux." (PMID 36778600, 2022).
cancer (continued). "HIF-1α is a key hypoxia regulator and pro-angiogenic factor that accumulates in cancer cells under hypoxic conditions and is involved in multiple events crucial for cancer metastasis, including cancer cell migration, invasion and angiogenesis." (PMID 36296726, 2022). "Therefore, HIF-1α can be a plausible factor contributing to resistance to carboplatin via alterations in cancer cell metabolism by enhanced MCT4 expression." (PMID 36012230, 2022). "Additionally, the silencing of HIF-1α can hinder the progression of cancer by inhibiting the expression of stem cell markers." (PMID 36014432, 2022). "Hypoxia-inducible factor-1 α (HIF-1α) is a key responser adapted to cancer hypoxia." (PMID 35310917, 2022). "The current study demonstrated a novel anti-cancer mechanism of apigetrin via HIF-1α in PCa." (PMID 35740392, 2022). "Many noncoding RNAs have been shown to dysregulate HIF-1α expression in cancer cells." (PMID 35642641, 2022). "The excessive accumulation of HIF-1α further exerts its cancer-promoting effect under hypoxia." (PMID 35928881, 2022). "Moreover, HIF-1α also encourages epithelial-mesenchymal transition and the acquisition of cancer stem cell-like characteristics in the bronchial epithelium." (PMID 36338690, 2022). "Previous studies have demonstrated that HIF1A is a potential target for cancer therapies." (PMID 36230822, 2022). "Increased HIF-1α expression induced by anti-angiogenic agents may contribute to increased aggressiveness of cancer cells at hypoxic niches." (PMID 35681691, 2022). "Succinate accumulated in matrix may leak to the cytosol, where it promotes cancer growth by stabilizing HIF-1α." (PMID 36344992, 2022). "In HCT116_ARNTLKO, we observed a phase-shift in differentially rhythmic transcript pairs (from cancer hallmark genes) including HIF1A and FGFR2 that were neither differentially rhythmic in HCT116_WT nor in other HCT116KO." (PMID 35552415, 2022). "Additionally, significantly higher expression was observed between groups distinguished by Youden’s J cut-off points for age, in the cancer group, for HIF1A (p = 0.0398) and EPAS1 (p = 0.0022)." (PMID 36230822, 2022). "HIF-1α inhibition might be a potential solution to enhance the chemo-/radiation therapeutic efficacy for cancer." (PMID 36011045, 2022). "Transcriptional regulation of different genes by HIF-1α in hypoxic cells may contribute differentially to the malignant phenotype in cancer cells." (PMID 36071871, 2022). "HIF-1α also acts as an oncoprotein in RB, and its knockdown led to increased expression of pro-apoptotic proteins, including Bax, caspase-9, and caspase-3, thus triggering apoptosis in cancer cells." (PMID 36619866, 2022). "Furthermore, it was found that BM macrophage efferocytosis of apoptotic cancer cells promotes higher HIF-1α stabilization when compared to apoptotic normal prostate epithelial cells." (PMID 36496973, 2022). "HIF-1-α promotes tissue repair but also proliferation of residual cancer cells." (PMID 35359377, 2022). "Studies have demonstrated that HIF-1α can reduce DNA damage in cancer cells through an unknown mechanism, further contributing to the drug resistance of several cancer types, including triple-negative breast cancer (TNBC) and prostate cancer (PC)." (PMID 35814435, 2022). "Then HIF-1α increases cancer drug resistance by increasing GLUT1." (PMID 36072596, 2022). "As DIM is a natural compound and it was previously proved that DIM has no side effects in patients and it has a profound effect on HIF-1α, it could be one of the potent therapeutics against cancer targeting HIF-1α." (PMID 36014432, 2022). "Hypoxia increasing HIF-1α expression and extravasation rates of cancer cells." (PMID 36439519, 2022). "The HIF-1α signaling pathway is a potential therapeutic target for cancer treatment." (PMID 35592530, 2022). "Cancer cells exposed to hypoxia, therefore, show high HIF1A activity." (PMID 36612058, 2022).